STX1A (syntaxin 1A)
Diseases named in the same sentence as STX1A in open-access papers (continued):
Sharing a sentence is not in itself a finding about the gene and the disease.
breast carcinoma (2 papers, 2016 to 2020). "Gene set analysis for STX1A expression also corroborated the results collected using the MicMa database: high STX1A expression associates with HER2-enriched and luminal B breast cancer subtypes." (PMID 26673618, 2016). "Very few information is available about the role of STX1A in cancer in general or in breast cancer in particular, although it forms part of the SNARE complexes, which seem to play a role in cancer cell migration." (PMID 26673618, 2016). "In addition, HRH1 and NRP2 should be considered interesting targets for the treatment of basal-related breast cancer subtypes, and STX1A could be an interesting target for the treatment of the luminal B and HER2-enriched subtypes." (PMID 26673618, 2016). "We propose that HRH1, NRP2, and STX1A can be used as prognostic biomarkers and therapeutic targets for basal and HER2-enriched breast cancer subtypes." (PMID 26673618, 2016). "High STX1A expression in luminal B and HER2-enriched tumors correlated with even lower overall survival and can therefore be considered an indicator of poor prognosis for this breast cancer subtypes." (PMID 26673618, 2016). "On the other hand STX1A had not been related to breast cancer." (PMID 26673618, 2016). "Therefore, therapies targeting HRH1, STX1A, and NRP2 might improve outcomes in basal-related breast cancer." (PMID 26673618, 2016). "Thus, we proposed that STX1A expression in HER2-enriched and luminal B breast cancer might favor the migration of cancer cells and invasion of the surrounding tissue." (PMID 26673618, 2016).
breast tumors (2 papers, 2016 to 2021). "The neurogenes HRH1 and NRP2 were upregulated in basal-related breast tumors and CD44+ cancer cells and another, STX1A, was upregulated in luminal B and HER2-enriched tumors." (PMID 26673618, 2016).
co-infection (2 papers, 2015 to 2022). "Only in one outbreak was found a co-infection case with another serogroup (outbreak 6: O111:NM stx1a/eae/ehxA); also 3 cases of BD and D were described as long carriers." (PMID 35336157, 2022).
dementia (2 papers, 2021 to 2024). Loss of intellectual abilities interfering with an individual's social and occupational functions. "Similarly, in the autopsy of patients with advanced AD and dementia, the level of Stx-1a protein in the prefrontal cortex neurons was decreased." (PMID 34732255, 2021).
Depression (2 papers, 2021 to 2023). "Taken together, these data suggest that the level of taurine associated with GluN2A and syntaxin 1A expression is involved in the development of depression." (PMID 35435537, 2023).
diarrheal disease (2 papers, 2016). The condition of having at least three loose or liquid bowel movements each day. "Shiga toxin (Stx) production, especially Stx1a, Stx2a, Stx2c, and Stx2d, has been implicated in causing severe disease and HUS, and STEC carrying Stx2b are mainly associated with diarrheal disease." (PMID 27047483, 2016).
Epileptic encephalopathy (2 papers, 2023). A condition in which epileptiform abnormalities are believed to contribute to the progressive disturbance in cerebral function. "Mutations in the syntaxin-1A (STX1A) gene have been linked to early-onset epileptic encephalopathy." (PMID 38003627, 2023).
glioma (2 papers, 2021). A benign or malignant brain and spinal cord tumor that arises from glial cells (astrocytes, oligodendrocytes, ependymal cells). "The correlation between CRNDE gene and PTX3 and STX1A genes has not been correlated for the time being confirmation in the literature, but PTX3 has been shown to be associated with poor prognosis in gliomas, and in connection with our results, its upstream target marker may be the CRNDE gene." (PMID 33767729, 2021).
Insulin resistance (2 papers, 2017 to 2021). Increased resistance towards insulin, that is, diminished effectiveness of insulin in reducing blood glucose levels. "Within 8 weeks of HFHSD, B6 mice became obese, developed impaired glucose tolerance and insulin resistance, and despite being hyperinsulinemic displayed non-compensatory insulin release, at least in part, due to reduced expression of syntaxin-1A." (PMID 33670429, 2021). "Both the candidate genes STX-1A and MLXIPL/ChREBP might be involved in the development of IGM and DM, accounting for β-cell dysfunction and insulin resistance, respectively." (PMID 29053727, 2017).
Intellectual disability (2 papers, 2023). "In all individuals with ultra rare variants in STX1A, intellectual disability, neonatal hypotonia and motor delay were present." (PMID 36564538, 2023).
memory impairment (2 papers, 2020 to 2022). "Since A/S/I-induced inattention, memory impairment and disorganized thinking may be due to synaptic dysfunction, we examined the effects of A/S/I on hippocampal mRNA expression of Snca α, STX1a and Ntrk1." (PMID 33088271, 2020).
type 2 diabetes (2 papers, 2019 to 2024). "In type 2 diabetes (T2D), severely reduced islet Stx1a levels contribute to insulin secretory deficiency." (PMID 39194497, 2024).
brain cancer (1 paper, 2019). A primary or metastatic malignant neoplasm affecting the brain. "STX1A has beenreported as tumor enhancer in brain cancers and small cell lung cancers, where itsexpression plays an important role in tumor formation." (PMID 30672978, 2019).
congenital heart disease (1 paper, 2024). A heart disease that is present at birth. "Among neonates with CIRCI requiring surgery for congenital heart disease with a post-operative cortisol level equal to or below 4.5 mcg/dL, 100% had a gene heterozygous mutation with loss of function in the STX1A gene from the SNARE family." (PMID 38275610, 2024).
Glucose intolerance (1 paper, 2021). Glucose intolerance (GI) can be defined as dysglycemia that comprises both prediabetes and diabetes. "In contrast to the glucose intolerance observed in STX1A-overexpressing mice, STX4-transgenic mice with 2–5-fold overexpression of STX4 in the skeletal muscle, adipose tissue, and pancreatic tissues, showed improved glucose homeostasis and islet function." (PMID 33673206, 2021).
Hyperglycemia (1 paper, 2021). An increased concentration of glucose in the blood. "These phenotypes were mostly due to the hyperglycemia-induced reduction in syntaxin-1A (Stx-1A) and SNAP-25 protein, since they could be recapitulated by the knockdown of endogenous Stx-1A and SNAP-25." (PMID 33937248, 2021). "We also showed that long-term hyperglycemia led to reduced SNAP-25 and syntaxin-1A expression, which may constitute the major factor for reshaping vesicle fusion dynamics." (PMID 33937248, 2021). "Correspondingly, knocking down syntaxin-1A and SNAP-25 in INS-1 cells decreased the fusion frequency, triggered more kiss-and-run events, and restricted the fusion pore size, which were similar to the effects of hyperglycemia." (PMID 33937248, 2021).
Hypokalemia (1 paper, 2021). An abnormally decreased potassium concentration in the blood. "Studies with primary cerebellar granule neurons exposed for MnCl2 identified potential axonal alteration due to hypokalemia and overexpression of STX1A, implicated in the production of presynaptic local proteins that regulate neurotransmitter release." (PMID 34941782, 2021).
ischemic heart disease (1 paper, 2019). "Stx-1A rs4717806 and rs2293489 haplotype analysis of distribution in ischemic heart disease (IHD) and Control group (CG) performed by Shesis plus software." (PMID 31192914, 2019). "SNAP25 rs36305, Stx-1A rs4717806, and rs2293489, VAMP2 26bp ins/del genotypic and allelic polymorphism distribution in patients with ischemic heart disease (IHD) and in the control group (CG)." (PMID 31192914, 2019). "SNAP25 rs36305, Stx-1A rs4717806, and rs2293489, VAMP2 26bp ins/del, Minor allele effect of association with ischemic heart disease (IHD) vs Control group (CG), calculated by regression analysis model with Shesis software." (PMID 31192914, 2019).
leiomyoma (1 paper, 2017). A well-circumscribed benign smooth muscle neoplasm characterized by the presence of spindle cells with cigar-shaped nuclei, interlacing fascicles, and a whorled pattern. "Levels of STX1A (P < 0.04), initially observed to increase, were significantly lower in luteal phase specimens of leiomyomas than proliferative phase specimens." (PMID 28637297, 2017).
multiple sclerosis (1 paper, 2019). A progressive autoimmune disorder affecting the central nervous system resulting in demyelination. "Similarly, Ddel polymorphism of SNAP-25 gene C/C genotype (p=0.059), syntaxin 1A T/C and C/C genotypes (p=0.005), and synaptotagmin XI gene C allele (p=0.001) were observed more frequently in patients with multiple sclerosis." (PMID 30582321, 2019).
non-small cell lung carcinoma (1 paper, 2022). A group of at least three distinct histological types of lung cancer, including non-small cell squamous cell carcinoma, adenocarcinoma, and large cell carcinoma. "In another study, STX1A was used to classify NSCLC (non-small cell lung cancer) patients into different prognostic groups." (PMID 36186431, 2022).
parasitic infection (1 paper, 2023). "Sufficient information on the role of MCM5, ATN1, SCNA and STX1A genes in the context of parasitic infection is not available." (PMID 37761803, 2023).
prion disease (1 paper, 2022). A transmissible disease that is caused by a protein that is able to induce abnormal folding of normal cellular proteins, leading to characteristic spongiform brain changes, which are associated with neuronal loss without an inflammatory response. "Synaptic proteins, including SNAP-25 and syntaxin 1A/1B, as well as signaling proteins, including calcium–calmodulin protein kinase 4 and mitogen-activated protein kinases (such as MAPK8), showed decreased expression in prion disease." (PMID 36378750, 2022).
progressive ataxia (1 paper, 2023). "Episodic Ataxia 2 is a rare disorder with an early onset characterized by progressive ataxia and one of the P/Q-channel mutations associated with EA2 is A454T, which was shown to have stronger inactivation coupled with a reduced modulation by Syntaxin 1A and SNAP-25, which reduced exocytosis." (PMID 37654674, 2023).
Retinal dystrophy (1 paper, 2015). Retinal dystrophy is an abnormality of the retina associated with a hereditary process. "We found that syntaxin-1A labeled the EPL in some regions of the retina despite extensive retinal dystrophy." (PMID 26092486, 2015).
Stroke (1 paper, 2022). Sudden impairment of blood flow to a part of the brain due to occlusion or rupture of an artery to the brain. "In addition, STX-1a blood levels correlated with the IS clinical scales National Institutes of Health Stroke Scale (NIH-SS) and the modified Barthel Index (BI)." (PMID 36008522, 2022).
type 1 diabetes (1 paper, 2024). "Also, NKX6.3, DLL4, SLC30A8, and STX1A, which play key roles in insulin synthesis and release, are predicted to be targeted by miR-214-5p, which was significantly upregulated in FOXA2-deficient islets, and has been previously reported to be associated with type 1 diabetes (T1D)." (PMID 38916841, 2024).
infection (36 papers, 2011 to 2026). The state of being infected such as from the introduction of a foreign agent such as serum, vaccine, antigenic substance or organism. "Several epidemiological studies have shown that infection with STEC isolates expressing Stx2a is more pathogenic than infection with strains producing Stx1a or Stx1a+Stx2a." (PMID 34208170, 2021). "In food samples, stx2c was the most commonly reported Shiga toxin subtype in developing countries, and it was also the fourth most prevalent subtype of human infection in Europe in 2022, following stx2a, stx1a, and stx2b, which highlights the ongoing risk of foodborne transmission of stx2c+ strains." (PMID 40732038, 2025). "Although in general infection of humans by stx2a may cause more severe clinical outcomes, a recent study in England indicated that presence of stx1a can also be associated with severe disease." (PMID 33858427, 2021). "Among the Stx1 subtypes, stx1c and stx1d are less commonly carried by STEC strains causing human infections than stx1a." (PMID 38674631, 2024). "Infection of the three-layer model with O26:H11 STEC strain TW08571 (Stx1a+ and Stx2a+), however, allowed translocation of modest amounts of Stx without reducing barrier function." (PMID 36977098, 2023). "We also recently found that the presence of Stx1a reduces the morbidity in Str-treated mice after infection with an STEC strain that makes both Stx1a and Stx2a." (PMID 32175286, 2020). "We hypothesize that JH2015 is avirulent in the mice due to the relatively low level of Stx2a produced during infection as indicated by the amount of cytotoxicity that remains after the Stx1a is neutralized (~102 CD50/g stool)." (PMID 32175286, 2020). "However, previous studies in our group have shown that Stx2a is the major toxin type released during EDL933 infection, whereas Stx1a remains in the periplasm." (PMID 29533744, 2018). "This implies that pretreatment with B. longum K5 alleviated the elevated expression levels of Stx1A and Stx2A induced by EHEC O157:H7 infection, underscoring the role of B. longum K5 in mitigating the effects of this infection." (PMID 38674854, 2024). "Nevertheless, mice infected with Stx1a+ Stx2a+ strain JH2015 and then treated with Cip released high levels of Stx2a into their stool and succumbed to the infection." (PMID 32175286, 2020). "Included in these isolates was the stx2c-only NSFO157 isolate from a 66-year-old patient and an O111 isolate recovered from an HUS patient with multi-strain infection where one strain was nleH1–2-positive (carrying stx1a and stx2a) and the other strain was negative (stx1a only)." (PMID 28391537, 2017).
tumor (17 papers, 1998 to 2024). "In this context, we assessed the clinical value of 8 genes (RAB2B, RAB3B, RAB9A, RAB11B, RAB27A, RAB27B, STX1A, and VAMP7), which are implicated in sEVs biogenesis, as well as their association with overall and tumor-derived plasma sEVs levels." (PMID 36980570, 2023). "The STX1 (SYNTAXIN 1A) pathway shows increased activity in W-CIN tumours." (PMID 35326573, 2022). "We identified five genes (ITGA5, MMP9, PTPRN, PTX3, and STX1A) that could significantly affect the OS rate of patients, and the difference between the tumor group and the normal group was statistically significant." (PMID 33767729, 2021). "Theseresults suggest that the enhanced expression of STX1A andVAMP2 might have role in triggering tumor progression inhigh grade stage III tumors." (PMID 30672978, 2019). "Our results showed that the expressionof STX1A and VAMP2 increased progressivelyaccording to the stage of the tumor." (PMID 30672978, 2019). "In addition, high tumor expression of RAB27A, RAB27B, RAB9A, RAB11B, and STX1A was favorable of a 5-year survival (p = 0.038, p = 0.015, p = 0.008, p = 0.002, and p = 0.028, respectively)." (PMID 36980570, 2023).
cancer (11 papers, 2013 to 2025). A tumor composed of atypical neoplastic, often pleomorphic cells that invade other tissues. "Our analysis of HRH1, NRP2, and STX1A expression using the GOBO database corroborated the overexpression of HRH1 and NRP2 in basal-like and HER2-enriched cancer subtypes, while STX1A was overexpressed only in HER2-enriched and luminal B subtypes." (PMID 26673618, 2016). "Apart from cell progression, STX1A and VAMP2have been reported to be regulatory proteins of the SNARE complex, involved in cellnavigation and migration and, hence, metastasis of cancer cells." (PMID 30672978, 2019).
neurodevelopmental disorder (5 papers, 2020 to 2024). A behavioral and cognitive disorder with onset during the developmental period that involves impaired or aberrant development of intellectual, motor, or social functions. "In this study, we describe eight individuals harboring ultra rare homozygous or de novo heterozygous variants in STX1A to delineate a novel STX1A-related neurodevelopmental disorder based on different pathogenic mechanisms and inheritance models." (PMID 36564538, 2023). "A previous study has shown that transcription factor YY1 binds to the promoter region of the Stx1a gene related to synaptic transmission and neurodevelopmental disorders and negatively regulates its transcription in a cell/tissue-specific manner." (PMID 35433684, 2022). "The HPC-1/syntaxin 1A (Stx1a) gene, which is involved in synaptic transmission and neurodevelopmental disorders, is a TATA-less gene with several transcription start sites." (PMID 33498722, 2021). "Therefore, one of its core proteins syntaxin 1A (STX1A) has long been suspected to play a role in neurodevelopmental disorders." (PMID 36564538, 2023).
psychiatric disorder (3 papers, 2020 to 2023). A disorder characterized by behavioral and/or psychological abnormalities, often accompanied by physical symptoms. "In the PPI network of these Egr targets in the DG region, the top key nodes tightly associated with distinct psychiatric disorders and addictive behaviors in previous studies included Syt1, Stx1a, Dlg4, Cplx1, Gria1, Snap25, Rab3a, and Bdnf81,86–91." (PMID 37758941, 2023). "TBR1 has also been associated with ASD and TCF4 with BPD, and TOP3B was shown to bind multiple mRNAs derived from ASD-linked genes, raising the possibility that STX1A-mediated neurotransmitter release is dysregulated in multiple psychiatric disorders." (PMID 31142819, 2021).
central nervous system diseases (1 paper, 2022). "The relationship between STX1A and central nervous system diseases is increasingly spotted." (PMID 36157213, 2022).
STX1A also shares sentences with these, for which no sentence is quoted: prostate carcinoma (20 papers); Burkitt lymphoma (5); colon carcinoma (5); colorectal cancer (4); Bovine mastitis (3); escherichia coli infection (3); Hereditary Prostate Cancer (3); mastitis (3); neurological disease (3); cardiovascular disease (2); Cognitive impairment (2); diabetes (2); gastroenteritis (2); hepatocellular carcinoma (2); intestinal infection (2); kidney failure (2); lymphoma (2); multiple myeloma (2); viral infections (2); acute cholecystitis (1); adrenal pheochromocytoma (1); adrenocortical adenoma (1); adrenocortical carcinoma (1); adrenocortical neoplasms (1); animal diseases (1); appendicitis (1); astrocytoma (1); atherosclerosis (1); autism spectrum disorder (1); bacteremia (1).
A further 59 diseases each share a sentence with STX1A in 1 paper.